IL18 (interleukin 18)
Diseases named in the same sentence as IL18 in open-access papers (continued):
Sharing a sentence is not in itself a finding about the gene and the disease.
Obesity (continued). "Obesity resulted in a marked increase in the expression of cyclooxygenase-2 (COX-2) and IL-6 in the adipose tissue of HFD animals, with concurrent moderate increases in TNF-α, IL-17A, and IL-18, while IL-1β changes were minor and inducible nitric oxide synthase (iNOS) expression was reduced." (PMID 38672413, 2024). "Similarly, mice lacking IL-18 gained 2–3 times more body weight per unit of energy consumed on a low- or high-fat diet, indicating the protective effect of IL-18 against obesity." (PMID 39769263, 2024). "In this study, with an obesity-related DCM mouse model established by feeding db/db mice with a high-fat diet (HFD), we observed increased mtDNA in the cytosol and activated cGAS-STING signaling pathway during DCM, as well as the downstream targets, IRF3, NF-κB, IL-18, and IL-1β." (PMID 35235096, 2023). "Expression of Ifi16 is significantly decreased in Il18−/− mice, which leads us to speculate that Ifi16 might not be related to obesity in Il18−/− mice." (PMID 38139000, 2023). "Moreover, when IL-18 null mice were exposed to HFD, the ensuing obesity phenotype was exacerbated." (PMID 33806797, 2021). "Most of the myokines measured were regulated by acute exercise (FGF21, IL-6, IL-8, IL-15, and IL-18), and some were released at different levels in plasma over the 24 h in the group of women with obesity in comparison to the non-obese group (SPARC, IL-8, and IL-13)." (PMID 32132925, 2020). "The role of IL-18 in metabolic syndrome, obesity, or diabetes is not clear." (PMID 31771099, 2019). "However, a lack of IL-18 or its receptor in mice induces hyperphagia, obesity and insulin resistance." (PMID 24733068, 2014). "Several reports have suggested that adipose tissue might not be the main source of IL-18 in patients with obesity and the metabolic syndrome." (PMID 20331890, 2010). "However, whether IL-18 is involved in the regulation of VC in CRF patients with obesity has not been reported yet." (PMID 34901204, 2021). "However, the role of IL-18 in metabolic syndrome, diabetes, or obesity is not clear." (PMID 29967666, 2018). "Since an interaction between OPN and IL-18 has not been studied in obesity, we investigated whether: (i) their levels were simultaneously elevated in obese individuals; (ii) OPN was associated with IL-18 in obese individuals and (iii) their levels associated with fasting blood glucose (FBG) and BMI." (PMID 23675517, 2013). "Therefore, the PCOS disease per se has correlation with IL-18, not dependent on IR and obesity." (PMID 21244650, 2011). "In contrast, and in agreement with previous reports, levels of IL-18 were found to be significantly increased among CWO displaying insulin resistance and were positively correlated with levels of obesity but not insulin sensitivity." (PMID 38467728, 2024). "Obese women with HI have considerably greater IL-18, although its levels are raised in PCOS patients irrespective of IR and obesity." (PMID 36677054, 2023). "In our study, serum IL-18 concentration was increased in PCOS patients irrespective of the presence or absence of IR and obesity." (PMID 21244650, 2011). "We hypothesize the change of IL-18 level in our study may contribute to the energy expenditure via PASET for obese persons, because Ye and McGuinness think inflammation during obesity is not all bad and promoted IL-18 may exerts a protective effect on limiting adiposity." (PMID 31548850, 2019).
atherosclerosis (213 papers, 2009 to 2025). A disease characterized by the build-up of fatty material and calcium deposition in the arterial wall resulting in partial or complete occlusion of the arterial lumen. "Elevated circulating IL-18 levels have been associated with accelerated atherosclerosis and the stimulation of pro-inflammatory cytokines that contribute to plaque destabilization in DM." (PMID 41382274, 2025). "The proinflammatory cytokine IL-18 has been implicated in the pathophysiology of atherosclerosis in preclinical models." (PMID 39451191, 2024). "In the context of atherosclerosis, IL-18 has been implicated in the inflammatory processes that contribute to the development and progression of atherosclerotic plaques." (PMID 38396639, 2024). "In ApoE−/− mice, the administration of IL-18 enhances atherosclerosis, whereas a deficiency of IL-18 signaling inhibits the process of atherosclerosis development and stability." (PMID 39685608, 2024). "Given its central role, the diagnostic and prognostic capabilities of IL‐18 in the context of atherosclerosis and coronary artery disease have garnered significant clinical and research interest." (PMID 38402570, 2024). "In fact, Il18 gene deletion and the forced expression of the IL-18 binding protein, a natural inhibitor of IL-18, both decreased atherosclerosis in apolipoprotein E-deficient mice." (PMID 39451191, 2024). "Plasma interleukin-18 (IL-18) is an inflammatory cytokine associated with macrophage activation and pyroptosis, plasma viral load, atherosclerosis, and CVD in symptomatic, HIV-infected patients and SIV-infected monkeys." (PMID 37965349, 2023). "For example, it has been described that visceral adipose tissue from patients with metabolic comorbidities show increased expression of IL1β, and IL18 has been associated with atherosclerosis and T2DM." (PMID 37867510, 2023). "IL-18 is linked to plaque instability in atherosclerosis, while IL-37 exhibits anti-inflammatory properties." (PMID 37637634, 2023). "Serum IL-18 played a major role in the establishment and development of atherosclerotic plaques in animal models of atherosclerosis and was associated with the plaque’s stability and severity." (PMID 35890100, 2022). "This is further supported by our finding: the levels of IL-18, a well-known proinflammatory cytokine associated with atherosclerosis, coronary artery disease, and myocardial IRI, increased only in the sham group, but not in the RIPC group." (PMID 34925697, 2021). "Deficiencies in IL-1β and IL-18 reduced the lesion size in an apolipoprotein E-deficient mouse model of atherosclerosis." (PMID 33534121, 2021). "Among the identified plasmatic proteins associated with subclinical atherosclerosis, we were particularly interested in the upregulation of IL-18 and the corresponding downregulation of TRAIL." (PMID 33936102, 2021). "In our previous study, we focused on the involvement of IL-18 in the immunoinflammatory processes underlying atherosclerosis." (PMID 32823917, 2020). "The authors reported reduced atherosclerosis, in spite of increased serum cholesterol, in IL-18 deficient apoE(−/−) mice." (PMID 30524759, 2018). "Our interest in the IL-18 engagement in the immuno-inflammatory processes underlying atherosclerosis is based on several important findings." (PMID 30400655, 2018). "This interaction leads to the secretion of IL-1β and IL-18, which have been associated with atherosclerosis severity." (PMID 30558209, 2018). "Previous studies have showed that increasing levels of IL-18 and IL-6 have been found to be involved in the pathogenesis of atherosclerosis and associated with future CV events and mortality." (PMID 28474577, 2017). "In the current study, using systems and clinical approach, the important role of IL-18 in the signaling pathways of atherosclerosis, that is the leading cause of morbidity and mortality worldwide, has been confirmed." (PMID 26669254, 2015).
atherosclerosis (continued). "In the present study we have also found a significant increase in frequency of GG-genotype when compared to GC and CC genotypes in CAD patients & FDRS indicating the role of IL-18–137 G/C polymorphism in development of atherosclerosis and its complications." (PMID 25822970, 2015). "On the basis of these results it can be concluded that IL-18 has a significant impact on the signaling pathways associated with atherosclerosis and its clinical consequences in patients with CKD." (PMID 26669254, 2015). "On the other hand, increased concentrations of IL-18 have been associated with several components of the metabolic syndrome and used as a factor in predicting diabetes, atherosclerosis, and cardiovascular disorders." (PMID 23781501, 2013). "Interleukin (IL)-18 has been associated with severity of atherosclerosis and discussed to predict cardiovascular (CV) events." (PMID 24040261, 2013). "In contrast to the pathogenic role of IL-1 and IL-18 in atherosclerosis pathogenesis, IL-33 has been described to attenuate cardiovascular inflammation and plaque formation." (PMID 23087690, 2012). "Increased IL-18 serum levels have been associated with diabetes type 2, metabolic syndrome and the severity of atherosclerosis." (PMID 22141572, 2011). "One study showed that elevated levels of IL-18 were associated with the presence of subclinical atherosclerosis evaluated with intima media thickness of the carotid artery, also after adjustment for traditional risk factors, CRP and IL-6." (PMID 20331890, 2010). "IL18R1 and IL18RAP genes code for two receptors of the IL-18 cytokine that has been found associated with atherosclerosis and its cardiovascular complications." (PMID 19473509, 2009). "In apoE knockout mice, administration of IL-18 has been associated with enhancement of atherosclerosis, whereas deficiency of IL-18 has been shown to reduce the extent of atherosclerosis." (PMID 19347053, 2009). "Interleukin-18 is a pro-inflammatory cytokine suspected to be associated with atherosclerosis and its complications." (PMID 19473509, 2009). "Additionally, the association between soluble ST2 and IL-18 expression in the aortic adventitia is noteworthy, given that increased IL-18 expression promotes atherosclerosis, whereas IL-18 deficiency has been shown to reduce it." (PMID 40943152, 2025). "Research suggests that IL-18 may play a role in plaque instability, making it a subject of interest in understanding the mechanisms underlying the complications of atherosclerosis, such as plaque rupture and thrombosis." (PMID 38396639, 2024). "Il-18 deficiency reduced the development of atherosclerosis in ApoE−/− mice." (PMID 35464402, 2022). "Furthermore, the deficiency of IL-18 in a mice model of atherosclerosis showed decreased atherosclerotic lesions." (PMID 35204152, 2022). "The serum IL-18 levels are associated with albuminuria and atherosclerosis in patients with T2D." (PMID 36263325, 2022). "Also, the major DAMPs including HMGB1 and S100B and their downstream signaling via TLR4 receptor have been intimately associated with the aggravated atherosclerosis resulting in the upregulation of proinflammatory cytokines including IL-18 and IL-1β." (PMID 35531433, 2022). "Similarly, the increased expression of IL-18 is associated with atherosclerosis, and it enhances atherosclerosis in association with IFN-γ." (PMID 35203642, 2022). "This screening allowed us to identify a plasmatic signature associated with subclinical atherosclerosis specific to PLWH that included the upregulation of IL-18 and IL-1β and downregulation of TRAIL, three important proteins with known functions in atherogenesis." (PMID 33936102, 2021). "IL-18 elicits a number of functions associated with aggravation of atherosclerosis." (PMID 33924019, 2021).
atherosclerosis (continued). "Previous studies have demonstrated that the interruption of IL18 function reduces atherosclerosis in mice, and loss-of-function mutations in CECR1 could lead to systemic vasculopathy or vasculitis." (PMID 34082770, 2021). "Pyroptosis is a new form of programmed cell death generated by some inflammasomes, piloting the cleavage of gasdermin (GSDM) and stimulation of dormant cytokines like IL‐18 and IL‐1β; these reactions are narrowly linked to certain diseases like diabetic nephropathy and atherosclerosis." (PMID 34369076, 2021). "IL-18 is a pleiotropic pro-inflammatory cytokine that affects both innate and acquired inflammatory responses, and it has been associated with the development of atherosclerosis by stimulating the production of atherogenic IFN-γ." (PMID 31661113, 2019). "Therefore, in order to investigate IL-18 contribution to the immuno-inflammatory processes underlying atherosclerosis, a systems approach has been used in our studies." (PMID 30400655, 2018). "Indeed, similar atherosclerosis phenotype changes because of diet differences (chow diet versus atherogenic diet) have been reported previously in the same male IL18-deficient Apoe−/− (Apoe−/−Il18−/−) mice." (PMID 28405010, 2017). "The results of our study suggest that active inflammation in the course of SpA is connected with an increased IL-18 level, which stimulates endothelial dysfunction and may increase the risk of atherosclerosis in this group." (PMID 27527149, 2016). "Moreover, the correlation between soluble ST2 and aortic adventitia IL‐18 expression is also pertinent given that increased IL‐18 expression exacerbates atherosclerosis 17, while IL‐18 deficiency reduces atherosclerosis." (PMID 26749303, 2016). "Moreover, circulating IL-18 levels can be utilized to predict the risk of atherosclerosis-related death in patients." (PMID 23087690, 2012). "Futhermore, some recent reports showed that IL18 might be correlated with atherosclerosis and served as a cardiovascular risk marker." (PMID 21244650, 2011). "Furthermore, it is associated with inflammatory state (CRP) and endothelial damage (sE-selectin), underlining the early development of atherosclerosis in overweight teenagers and the connecting role of inflammation mediated by factors such as IL-18." (PMID 20169140, 2010). "The hypothesized mechanism by which IL-18 may be linked to CVD risk is related to atherosclerosis and its complication." (PMID 19473509, 2009). "Therefore, understanding the role of IL-18 and its mechanisms of action may offer novel insights into therapeutic strategies for atherosclerosis development and subsequent clinical complications caused by a plaque rupture." (PMID 39451191, 2024). "Given that inflammation is a significant risk factor for atherosclerosis and the associated macrovascular and microvascular complications, we hypothesized that the mRNA expression of IL-18 and IL-18-BP, along with rs187238 SNP, may have a significant role in CAS development." (PMID 29485097, 2018). "Interleukin 18 (IL-18), fetuin-A, soluble intercellular adhesion molecule-1 (sICAM-1), and endothelin-1 (ET-1) are a group of cytokines and adhesion molecules which activate and deregulate endothelial function, and could increase the risk of atherosclerosis." (PMID 27527149, 2016). "Pyroptosis, which is mediated by caspase-1-dependent inflammasome activation and gasdermin proteins, amplifies local and systemic inflammation, accelerating atherosclerosis by releasing inflammatory cytokines such as interleukin (IL)-1β and IL-18." (PMID 39898976, 2025).
atherosclerosis (continued). "Knockout of NLRP3, ASC, and IL-1α/β significantly mitigated early atherosclerosis and IL-18 levels when subjected to a Western-style high-cholesterol diet." (PMID 41194915, 2025). "We therefore consider NLRP3 a promising therapeutic target in atherosclerosis, as it combines classic inflammasome inhibition—reducing IL-1β and IL-18 release—with direct anti-proliferative effects on plaque macrophages." (PMID 40956333, 2025). "We therefore investigated the direct role of Tfh cells and the role of IL18 in Tfh differentiation in atherosclerosis." (PMID 38381113, 2024). "Lymphocytes, in the form of B and T cells, B lymphocytes, and Th2 cells, have atheroprotective effects, whereas especially Th1 cells, induced by IL-12 and IL-18, enhance atherosclerosis damage." (PMID 38592104, 2024). "IL‐18 plays an intricate role in inflammatory conditions, encompassing autoimmune disorders, infectious diseases, and atherosclerosis." (PMID 38402570, 2024). "It has been proposed that pro-inflammatory cytokines, including IL-8 and IL-18, play crucial roles in the initiation, progression and complications of atherosclerosis (AS)." (PMID 39766338, 2024). "We identified a set of genes (GSDMD, CASP1, NLRC4, AIM2, and IL18) closely related to atherosclerosis, particularly in atherosclerotic lesions with high pyroptosis scores." (PMID 38167983, 2024). "IL-18 is a proinflammatory pleiotropic cytokine, whose increased expression has been shown to play a role in the development and progression of atherosclerosis." (PMID 39451191, 2024). "We used IHC to preliminarily detect the expression of GSDMD, CASP1, NLRC4, AIM2 and IL18 in advanced atherosclerosis plaques of patients." (PMID 38167983, 2024). "Here, we show that exposure to IL-18 promotes the proliferation, migration, and proinflammatory phenotype switching of ASMCs, all of which contribute to atherosclerosis development." (PMID 39451191, 2024). "In this study, we assessed the serum levels of TRAIL, IL-18, and OPG in over a thousand patients to determine associations between these markers, cardiac risk factors, and atherosclerosis burden." (PMID 39334884, 2024). "The elevated levels of IL-18 have been observed in individuals with atherosclerosis, and it is considered a potential biomarker for assessing the inflammatory status associated with cardiovascular disease." (PMID 38396639, 2024). "Both IL-1β and IL-18 exert pro-inflammatory effects through the nuclear factor kappa-light-chain-enhancer of activated β cells (NF-κβ) pathway and are involved in the atherosclerosis process." (PMID 36753488, 2023). "Recent research has identified IL-1β and IL-18 as the most important inflammatory cytokines that promote atherosclerosis development." (PMID 37374202, 2023). "This includes but is not limited to instances such as influenza virus infections, atherosclerosis, diabetes, chronic obstructive pulmonary disease, and Crohn's disease, where there exists ample evidence of IL-18's pivotal roll." (PMID 38260156, 2023). "The NLRP3 inflammasome activates caspase-1, acts on the precursor molecules of IL-1β and IL-18, and promotes the maturation and secretion of IL-1β and IL-18 to trigger an inflammatory response and further aggravate atherosclerosis." (PMID 37679676, 2023). "In APN-treated atherosclerosis mice, the inflammatory cytokines IL-1β and IL-18 were significantly decreased." (PMID 37198205, 2023). "First, it is important to underline that in mice with advanced atherosclerosis, activation of the dsDNA sensing AIM2 inflammasome induced a marked release of the proatherogenic cytokines IL-1β and IL-18." (PMID 36672621, 2023). "The role of NLRP3 inflammasome activation in atherosclerosis and atherogenesis can be understood by the role of two terrible cytokines produced by it, i.e., IL-1β and IL-18." (PMID 36851139, 2023).